CRP (C-reactive protein)
Diseases named in the same sentence as CRP in open-access papers (continued):
Sharing a sentence is not in itself a finding about the gene and the disease.
COVID-19 (continued). "Besides profiling the COVID-19-related IgG glycosylation changes, the aim of our study was to determine whether observed alterations are associated with patients age and whether they correlate with changes in CRP and anti-SARS-CoV-2 IgG plasma concentrations." (PMID 35495660, 2022). "Both CRP-to-albumin ratio and CRP-to-lymphocyte ratio showed good performance in assessing 30-day mortality in KTR with COVID-19." (PMID 36556433, 2022). "Several hematological laboratory investigations have shown that lymphocytes, neutrophils, CRP, elevated D-dimer, and hemostasis are altered significantly in COVID-19 patients." (PMID 35891295, 2022). "In COVID-19, IL-6 and CRP showed very high discriminative utility with an AUC of 0.899 (95%CI 0.850–0.948) for IL-6 and 0.922 (95%CI 0.879–0.946) for CRP, respectively." (PMID 35622838, 2022). "Besides CRP apheresis, approaches aimed at inhibiting either CRP dissociation into mCRP or antibodies against mCRP could represent attractive alternatives to prevent the cytokine storm and hyperinflammatory status associated to COVID-19." (PMID 36741367, 2022). "In an observational cohort study of patients with COVID-19, all of the following biomarkers were measured: Troponin I, B-type natriuretic peptide, C-reactive protein, ferritin, and d-dimer." (PMID 35281265, 2022). "This inverse relationship between ILC abundance and CRP was also evident in children with COVID-19 or MIS-C." (PMID 35275061, 2022). "The risk variables related to the mortality of patients with COVID-19 were age, gender, comorbidity with cardiovascular disease, WBC, lymphocytes, neutrophils, NLR, PLT, CRP, PT, APTT, D-dimer, and DLR (p < 0.05)." (PMID 36590587, 2022). "A more recent study indicated that serial CRP, neutrophil, and lymphocyte counts during the first three days of hospitalization can estimate supplemental oxygen requirement in patients with COVID-19." (PMID 36441688, 2022). "In patients with COVID-19 strong positive correlations were found between plasma levels of hs-CRP and AAT (r = 0.7, p < 0.001), and between HP and AGP (r = 0.61, p < 0.01)." (PMID 36514048, 2022). "A systematic review and meta-analysis of 23 studies found that in patients with severe COVID-19, high values of procalcitonin, C-reactive protein, D-dimer, and lactic dehydrogenase were found, as well as low values of albumin." (PMID 35601226, 2022). "C-reactive protein (CRP) has been one of the most used biomarkers to assess the evolution of COVID-19 inflammatory processes, even though its use is limited by a low sensitivity for community-acquired pneumonia (CAP)." (PMID 36010321, 2022). "A significantly higher neutrophil count, CRP levels and lower lymphocyte counts were observed in pregnant COVID-19 infected females." (PMID 35371473, 2022). "In patients with COVID-19, higher serum C-reactive protein, interleukin-6, and LDH levels, which correlated with disease severity, were observed in the diabetic group with hyperglycemia than in the non-diabetic group." (PMID 35836103, 2022). "Statistically significant correlations were found between troponin values and specific parameters of COVID-19, such as PaO2/FiO2 (expression of respiratory failure), D-dimer, CRP, and lymphocytes (expression of inflammation during infection)." (PMID 35566664, 2022). "CRP is an inexpensive, widely available test used in COVID-19 pediatric patients for early recognition of neurological presentations for early and adequate treatment." (PMID 36420294, 2022). "The recent COVID-19 group had significantly higher neutrophils and CRP levels, and significantly lower prothrombin than the other two groups." (PMID 36325669, 2022). "AST (p<0.0001), LDH, ferritin, D-dimer, and CRP were found to be significantly different amongst mild, moderate and severe COVID-19 subjects (p<0.0001 for all)." (PMID 36475201, 2022). "SAA, IL-6, and CRP showed strong sensitivity and specificity in predicting the severity and prognosis of COVID-19." (PMID 35958594, 2022).
COVID-19 (continued). "Two case reports describe decreasing IL-6 and CRP after onset of electrical VNS in four COVID-19 patients suffering from moderate or severe COVID-19-pneumonia." (PMID 36263035, 2022). "Out of 201 patients with PCR confirmed SARS-CoV-2 infection, 53 patients were those with severe acute COVID-19 pneumonia and elevated serum markers of COVID-19 severity such as D-Dimer, CRP, and ferritin." (PMID 36136963, 2022). "Meanwhile, it was suggested that high levels of CRP and lung involvement, as well as low levels of oxygen saturation and lymphocyte count, were highly related to cardiac injury in COVID-19 patients." (PMID 35149778, 2022). "This viremia and virus replication results in serious symptoms, one of which is the triggering of cytokine storms, including interferon-alpha, IL-2, IL-6, IL-10, and C-reactive protein, which can erode the health of COVID-19 patients." (PMID 35812166, 2022). "Eventually, we found that as the age of teachers increases, the strength of the relationship between CRP and teachers’ perceptions of the impact of COVID-19 on relationships increases (respectively β = 0.18; 0.20; 0.24; p < 0.001)." (PMID 36141916, 2022). "Many of the APPs (ALB, ORM, CRP among others) appear in the routine clinical analysis (by conventional immunoassays) of hospitalized patients and can be applied to stratify COVID-19 patients according to the severity." (PMID 35154090, 2022). "CRP levels were elevated in patients with COVID-19 and correlated positively with disease severity and mortality." (PMID 36366539, 2022). "These actions provide an ameliorated immune environment and reduce the severity of COVID-19 illness, further reflected by laboratory inflammatory markers (CRP, WBC count) as observed in our study." (PMID 35865966, 2022). "In the present study, we found that BMI, D-dimer, CRP, creatinine and pyruvate levels were the main determinants of COVID-19 severity." (PMID 36189213, 2022). "Biomarkers related to COVID-19 severity, such as CRP, D-dimer, LDH, and IL-6 levels, were higher in patients in the severe group than in those in the non-severe group." (PMID 35816225, 2022). "The most interesting findings of our study were elevated levels of plasma exosome-associated NE in COVID-19 patients compared to healthy controls and its correlation with elevated levels of AAT, CRP, and LDH concentrations in the plasma." (PMID 36084115, 2022). "According to a prospective study, the gut microbial composition was correlated with the increase of inflammation markers, including interleukin (IL)-10, tumor necrosis factor-α, and C-reactive protein (CRP) in COVID-19 patients." (PMID 35045853, 2022). "Our study examined the correlation of ESR with disease severity and mortality in COVID-19 and the superiority of C-reactive protein (CRP) to interrogate its necessity." (PMID 35992514, 2022). "In patients with severe COVID-19, C-reactive protein (CRP) levels in the blood are markedly elevated." (PMID 36078094, 2022). "In the present study, we found that increased CRP, IL-6, KL-6, HMGB-1, and d-dimer levels and decreased platelet counts early after admission were associated with the start of MV due to COVID-19." (PMID 35204430, 2022). "Several studies have shown that classic inflammatory markers, such as C reactive protein (CRP), procalcitonin, D-dimer, LDH and ferritin, are significantly associated with a poor prognosis in COVID-19 patients." (PMID 36292243, 2022). "Considering elevations in CRP levels have been associated with acute thrombotic episodes in the general population, it follows that it would also be associated with VTE in COVID-19." (PMID 36177015, 2022). "The univariate logistic regression analysis showed that older age, female sex, and increased CRP, PCT and D-dimer were associated with the severity of COVID-19." (PMID 36619998, 2022).
COVID-19 (continued). "There are abundant studies that analyse the behaviour of laboratory markers in patients hospitalised for COVID-19, some of them coinciding with the markers analysed in this study: D-dimer, glucose, serum ferritin, and C-reactive protein." (PMID 35564749, 2022). "The well-studied COVID-19 severity biomarkers, serum CRP and d-dimer, were elevated in MP and non-MP groups on admission (CRP>10 mg/L, d-dimer>1000 μg/L), and albumin was decreased (Alb<40 g/L)." (PMID 35350784, 2022). "In COVID-19 there is a systemic inflammatory phase in which inflammatory biomarkers, such as CRP, ferritin, PCT, D-dimer, and LDH are markedly elevated." (PMID 35799750, 2022). "Common laboratory findings in COVID-19 patients include leucopenia (and often leucocytosis), elevated serum D-dimer, ferritin, and C-reactive protein (CRP) levels." (PMID 36494866, 2022). "In this study, the elevated CRP was observed in 86% of severe COVID-19 patients and more than 60 mg/L of CRP was reported as a cut-off point and thrice tendency for higher mortality (OR: 3.025, 95% CI 0.931–9.827) (p: 0,08)." (PMID 35991587, 2022). "The C-reactive protein levels, D-dimer, and serum ferritin were high in this patient, reflecting the COVID-19 status." (PMID 35869470, 2022). "Elevated CRP level indicates the severity of COVID-19 in many cases, and it has been introduced as the main predictor for mechanical ventilation in patients with COVID-19 and reflects inflammatory reaction." (PMID 35958125, 2022). "The principal pathophysiology indicates a cardio-inflammatory response, as many significantly ill COVID-19 patients determine concomitant elevations in acute phase reactants such as CRP and the natriuretic peptides." (PMID 35281265, 2022). "Lower lymphocyte count, higher neutrophils count, and higher c-reactive protein levels among patients with poor outcomes were documented in this study and reported by several other COVID-19 studies." (PMID 36111328, 2022). "Our data suggest that NP synthesis is upregulated at the early phase of infection by a distinct pathway and/or cells from those of CRP and IL-6 in patients with COVID-19." (PMID 35529699, 2022). "CRP, measured with a high-sensitivity method, was chosen as a possible marker of a sustained post-COVID-19 inflammatory state resulting in endothelial activation and damage." (PMID 36362687, 2022). "Earlier case series have reported RV dilation to be present in as much as 41% of patients with COVID-19 induced ARDS and 27% of patients had impaired RV function and identified C-reactive protein (CRP) and D-dimer as associated biomarkers of RV dysfunction." (PMID 36335383, 2022). "The study identified seven risk factors for severe COVID-19: older age, higher LDH, CRP, direct bilirubin (DBIL), red blood cell distribution width (RDW), BUN, and lower albumin (ALB)." (PMID 36010198, 2022). "In our study, the variables associated with death were older age, higher Charlson comorbidity index, COVID-19 severity, lower O2 saturation, higher inflammation markers (e.g., CRP, ferritin), and leucocyte and NLR values, as well as lower lymphocyte count." (PMID 35743662, 2022). "Fibrinogen (5.48 g/L vs 2.88 g/L, P <0.00001) and CRP (87 mg/L vs 1 mg/L, P <0.00001) are also increased in COVID-19 patients compared to HS." (PMID 36441730, 2022). "There are also a number of studies that suggest that high CRP concentration increases mortality chance in COVID-19 patients." (PMID 36585718, 2022). "When conducting tests for LA, there are some disadvantages, with the most important being the interference of CRP and anticoagulation therapy, which are both present in COVID-19 patients." (PMID 36295093, 2022). "It proved that if an individual is already positive for COVID-19, as their Vitamin D levels increased, the levels of inflammatory markers such as D-Dimer and C-reactive protein decreased along with the extent of lung injury." (PMID 35401518, 2022).
COVID-19 (continued). "A statistically significant difference was found in WBC, lymphocyte, neutrophil, neutrophil/lymphocyte ratio, alanine aminotransferase (ALT), and CRP parameters in the normal delivery group between the COVID-19 and normal pregnant groups." (PMID 36263236, 2022). "Elevated levels of C-reactive protein, interleukin-1B, and interleukin-6 have become key signatures of severe COVID-19." (PMID 36431059, 2022). "All patients reported here were diagnosed with the severe course of COVID-19 and CRP apheresis was initiated within 72 h of this onset." (PMID 35407564, 2022). "Accordingly, acute VTE is known to be associated with classical inflammatory responses and elevations of CRP, and indeed VTE risk is elevated in conditions associated with inflammation, such as inflammatory bowel disease, COVID-19 and sepsis." (PMID 36177015, 2022). "Consistent with recent reports, troponin I and CRP levels were in the normal range in the majority of our cohort with mild/asymptomatic COVID-19." (PMID 35751748, 2022). "Elevated inflammatory markers, including IL-6, CRP, ferritin, and D-dimer have been reported in severe COVID-19." (PMID 35864532, 2022). "As expected, antibiotic prescribing increased significantly with increasing severity of COVID-19 (p < 0.001), elevated WBCs (p < 0.001) and CRP levels (p < 0.001) as well as the need for oxygen therapy (p < 0.001)." (PMID 35740195, 2022). "Potential explanations for this include a baseline level of inflammation in periodontitis patients, with periodontally compromised COVID-19 patients having higher levels of C-reactive protein (CRP)." (PMID 35208609, 2022). "Age, male sex, viral load, DM, dementia, low hemoglobin, white cell count, serum creatinine, CRP, and D-dimer levels at presentation were independent risk factors for ICU admission in COVID-19 patients (P < 0.05, for all)." (PMID 36714113, 2022). "Authors observed decreased microbiota richness in the acute disease compared with the control group (N = 30), and higher CRP and disease severity (in acute phase) in the same post-COVID-19 patients with lower microbiota diversity." (PMID 36011823, 2022). "C-reactive protein is an acute phase protein and is high in severe COVID-19 patients that can be considered as a valuable biomarker." (PMID 35168674, 2022). "Although elevated in most COVID-19 patients, C-reactive protein and procalcitonin levels were higher in patients with primary co-infections than in those without (median CRP 110 mg/l, IQR 51–222 vs. 36, IQR 11–101, respectively; p < 0.0001)." (PMID 35420370, 2022). "We also enrolled 10 children with atypical KD for comparison with those with COVID-19 and found significantly higher levels of CRP, WBCs, and procalcitonin in KD than in COVID-19 (p < 0.05) and lower hemoglobin in KD (p < 0.05)." (PMID 35626814, 2022). "Our results (three pooled studies with 173 patients) found a significant decrease in the CRP serum levels as an endpoint following Omega-3 supplementations in COVID-19 patients compared to the control." (PMID 36064554, 2022). "The recent COVID-19 group had significantly higher levels of neutrophils (P = 0.008), CRP (P = 0.009), and LDH (P = 0.009), while white blood cell count was similar among the groups (P = 0.438)." (PMID 36325669, 2022). "In COVID-19 patients, endocan was significantly but moderately correlated with CRP, neutrophil count, neutrophil/lymphocyte ratio and D-dimer values." (PMID 36233427, 2022). "However, when assessing the composite of critical COVID-19 using logistic regression models, lower vitamin D levels were associated with critical COVID-19 (OR 0.97, 95%CI 0.94, 0.99, p = 0.042, adjusting by age, gender, BMI, C-reactive protein, D-dimer, CKD, SpO2 or T2D status)." (PMID 35155539, 2022). "In patients with COVID-19 and other respiratory infections, inflammatory biomarkers harbour strong prognostic information, particularly IL-6 and CRP." (PMID 35622838, 2022).
COVID-19 (continued). "And other findings about the C-reactive protein (CRP) revealed a positive correlation with the severity of COVID-19." (PMID 35592303, 2022). "Of note, high CRP (above ROC-defined cutoff), LDH and fibrinogen were independently associated with critical COVID-19 when entered in a multivariable analysis." (PMID 35407418, 2022). "Meanwhile, laboratory parameters can predict COVID-19 prognosis and bacterial co-infection through C-reactive protein and procalcitonin." (PMID 36365001, 2022). "Elevated routine blood test parameters (C-reactive protein (CRP), fibrinogen) and suPAR serum level were independently associated with more severe lung damage in COVID-19 patients." (PMID 36555850, 2022). "A Chinese study evaluated the cognition of 29 patients with COVID-19, correlating cognitive complaints to high C-reactive protein (CRP) levels during the disease's acute phase." (PMID 36046159, 2022). "At the same time, we observed a negative correlation between the levels of D-dimer, ferritin, and CRP, known to be prognostic factors for COVID-19, and serum adropin levels in the present study." (PMID 35703530, 2022). "The aim of the study was to evaluate the vitamin D status in hospitalized COVID-19 patients and the correlation with C reactive protein (CRP), ferritin, fibrinogen, and peripheral blood leukocytes, as well as inflammatory derived indices." (PMID 35631138, 2022). "In the moderate-severe COVID-19 group, fibrinogen, CRP, and body temperature values were significantly lower than in the mild COVID-19 group (p < 0.05)." (PMID 36326345, 2022). "In the context of the SARS-CoV-2-induced disease COVID-19 it is remarkable that CRP plasma levels rise to an extent similar to bacterial infections." (PMID 35407564, 2022). "Another strength is represented by the performance of multivariate statistical analysis, with the adjustment of the results to patient sex, age, BMI, CRP, blood oxygen saturation level, the severity of COVID-19, and pre-existing liver disease." (PMID 36296321, 2022). "Patients with severe COVID-19 exhibit substantial immune changes including lymphopenia and increased blood levels of inflammatory biomarkers such as C-Reactive Protein (CRP), IL-1β, TNF-α, IL-8, and IL-64–8." (PMID 35064122, 2022). "Correlation between COVID-19-related differences in total and anti-S IgG1-specific glycosylation traits and the difference in CRP and anti-S IgG plasma concentration in COVID-19 patients." (PMID 35495660, 2022). "To further delineate the relationship of gene expression with inflammation status, we next determined the plasma levels of C-reactive protein (CRP), which is an established clinical marker of systemic inflammation among COVID-19 patients." (PMID 36377893, 2022). "A history of ICI within 90 days and elevated CRP (≥ 2.75 mg/dL) levels are potential factors leading to respiratory failure in COVID-19-affected patients undergoing chemotherapy for lung cancer." (PMID 36316726, 2022). "Patients with COVID-19 at the ICU had significantly higher C-reactive protein (CRP) levels, an acute phase reactant and a sensitive marker of an increased inflammatory state." (PMID 35355988, 2022). "Cytokine storm, characterized by massive release of IL-6 and other cytokines, frequently developed in severe COVID-19, leading to a marked elevation of CRP." (PMID 36035233, 2022). "In this retrospective cohort study of a racially diverse patient population hospitalized for COVID-19 who had marked elevations and interval changes in CRP levels, we found that an elevation of CRP levels was associated with a prolongation of the QTc interval." (PMID 35811700, 2022). "Our findings revealed that COVID-19 patients with higher CRP levels and lower PH had higher mortality and poor nutritional condition." (PMID 36585718, 2022).